NPNT (nephronectin)
Description:
Functional ligand of integrin alpha-8/beta-1 in kidney development. Regulates the expression of GDNF with integrin alpha-8/beta-1 which is essential for kidney development. May also play a role in the development and function of various tissues, regulating cell adhesion, spreading and survival through the binding of several integrins (By similarity).
Synonyms: EGFL6L; POEM
Tractability: Antibody: UniProt places it where antibodies can reach, with medium confidence; UniProt predicts a signal peptide or a membrane-spanning region; its Gene Ontology location is reachable by antibodies, with medium confidence. PROTAC: ubiquitination databases record sites on it.
Gene: Protein-coding gene on chromosome 4 (105,894,775 to 106,004,027, forward strand). Ensembl gene ENSG00000168743.
Subcellular location: Secreted, extracellular space, extracellular matrix
Subcellular location (Human Protein Atlas): Cell Junctions; Cytosol; Nucleoplasm; Predicted to be secreted
Pathways (Reactome):
Developmental Biology: Formation of the nephric duct; Formation of the ureteric bud
Gene Ontology:
Molecular function: extracellular matrix structural constituent; integrin binding; calcium ion binding
Biological process: branching involved in ureteric bud morphogenesis; cell-cell adhesion mediated by integrin; cell-matrix adhesion; cellular response to tumor necrosis factor; extracellular matrix organization; positive regulation of cell-substrate adhesion; positive regulation of ERK1 and ERK2 cascade; positive regulation of osteoblast differentiation; ureteric bud development
Cellular component: extracellular exosome; extracellular matrix; extracellular region; membrane
Genetic constraint (gnomAD): Loss-of-function variants: 35 observed, 49.16 expected, observed/expected ratio (o/e) 0.71, 90% interval 0.54 to 0.94. The upper end of that interval is the gene's LOEUF score, 0.94, which puts it in group 4 of 6, group 1 being the genes least tolerant of losing a copy. Missense variants: 542 observed, 579.02 expected, observed/expected ratio (o/e) 0.94, 90% interval 0.87 to 1. Synonymous variants: 195 observed, 209.77 expected, observed/expected ratio (o/e) 0.93, 90% interval 0.83 to 1.05.
Homologues: Orthologues: chimpanzee NPNT (99% identical), macaque NPNT (93% identical), pig NPNT (91% identical), dog NPNT (89% identical), mouse Npnt (87% identical), rat Npnt (85% identical), guinea pig NPNT (79% identical), rabbit NPNT (78% identical), tropical clawed frog npnt (66% identical), zebrafish npnta (58% identical). Paralogues in human: EGFL6 (37% identical).